TNF (tumor necrosis factor)
Diseases named in the same sentence as TNF in open-access papers (continued):
Sharing a sentence is not in itself a finding about the gene and the disease.
pneumonia (continued). "In agreement with previous reports, we confirmed that the proinflammatory cytokines IL-6, TNF-α, and IL-1β accumulated in the lungs of PmCQ2-infected mice, which is a typical response to pneumonia." (PMID 38589976, 2024). "TNF‐neutralizing antibody reduced Dusp1 and Ptprs levels in AM from aged mice and reduced pneumonia severity following bacterial challenge." (PMID 38459711, 2024). "Lung tumor necrosis factor-α, interleukin (IL)-1β, IL-6, and IL-10 were significantly decreased at 48 hours after pneumonia induction in the exercise group compared with the control group." (PMID 38193770, 2024). "The administration of phages in control non-pneumonia mice indicated the safety of phage treatment and the reduced inflammatory cytokines (TNF-α and IL-6) in the serum of pneumonia mice supported the downregulation of proinflammatory cytokines by phages." (PMID 39012882, 2024). "The secretion of IFN-γ and TNF-α via lung cells has been correlated with protection against pneumonia." (PMID 38400107, 2024). "TNF-α and IL-1β are two key pro-inflammatory cytokines, the increased concentration of which often indicates the severity of pneumonia and the intensity of the inflammatory response." (PMID 37446875, 2023). "We collected sera from healthy physical examiners, children with KD, and children with pneumonia and measured the levels of TNF‐α, IL‐1β, NLRP3, and LL‐37 in serum." (PMID 37773705, 2023). "In accordance with this, higher systemic levels of pro-inflammatory cytokines, such as IL-6 and TNF, at discharge can predict both short and long-term mortality after hospitalization for pneumonia." (PMID 36870980, 2023). "Macrolides have been shown to regulate cytokines such as tumor necrosis factor α, interleukin 1, interleukin 6, interleukin 8 and interferon γ, which play an important role in host defense mechanisms in patients with pneumonia." (PMID 36910529, 2023). "In particular, there was a significant increase of tumor necrosis factor (TNF)-α in the BALF of pneumonia patients." (PMID 36923935, 2023). "The STAT3 cytokine signaling pathway is downstream of the NF-κB pathway, and dysregulated TNF levels cause hyperactivation of STAT3, which also correlated with severe pneumonia during respiratory ectromelia virus (ECTV) infection." (PMID 36851532, 2023). "MRSA-induced pneumonia feces recipients exhibited a trend toward higher bronchoalveolar lavage fluid (BALF) TNF-α, IL-6, IL-1β, CXCl-1, MCP-1 levels, and W/D ratio." (PMID 37823635, 2023). "Multiple pro-inflammatory cytokines have been detected to have a certain amount of expression in the pneumonia model, such as TNF-α, IFN-γ, IL-1β, and IL-6." (PMID 36707501, 2023). "The levels of serum cytokines including CXCL10, IL-2, and TNF-α appeared to be correlated with the severity of pneumonia." (PMID 36949406, 2023). "We used the antiviral oseltamivir and the anti-inflammatory drug etanercept to dampen TNF signaling after the onset of clinical signs to treat pneumonia in a mouse model of respiratory IAV infection." (PMID 36851532, 2023). "In this study, we analyzed the levels of serum IL‐6, IL‐8, IL‐10, IL‐1β, sIL‐2R and TNF‐α in children with pneumonia." (PMID 37142438, 2023). "A prolonged febrile illness or pneumonia in patients treated with TNF-α inhibitors should trigger physicians to consider Histoplasma capsulatum infection as a possible cause of illness, especially when the patient had traveled to endemic regions." (PMID 36104715, 2022). "Further targeted metabolomic assays reveal the elevated level of glutamine, which is synthesized by intestinal K. pneumonia to indirectly exert effects on MM, and leads to the elevated secretion of TNF-α in the lung, thereby promoting pneumonia in MM." (PMID 36077725, 2022). "Consistent with the previous findings, we found that levels of a variety of cytokines, such as IL-6, IL-1RN, and TNF-α, increased rapidly in the pneumonia cases, thereby accelerating the inflammatory response." (PMID 36119044, 2022).
pneumonia (continued). "Accordingly, in our work, we observed that key inflammatory markers (IL-6, TNF-α, IL-8, IL-1α, and IP-10) were elevated in serum from hospitalized women due to severe features, such as pneumonia." (PMID 36016660, 2022). "So, it is acceptable to define the TNF signaling pathway of pneumonia as a critical therapeutic target of YHPGKL, which is necessary to analyze in the future." (PMID 36389108, 2022). "Treated animals showed a significantly higher percentage of lymphocytes positive to IFNγ around blood vessels and airways, as well as in the airway epithelium, while TNFα immunostained macrophages were significantly more numerous in areas of pneumonia." (PMID 36671276, 2022). "Pneumonia is characterized by the production of inflammation-related cytokines and chemokines throughout the body, especially in the lungs, including TNF- α, IFN- γ, IL-6 and IL-1β which are controlled by TLR4/NF-κB signaling pathway." (PMID 36530439, 2022). "Two infants exposed to anti-TNFα monotherapy (1 discontinued at week 30, 1 continued throughout pregnancy), had one event of pneumonia, and one was clinically diagnosed with pertussis despite immunizations, at age 10 months." (PMID 36120653, 2022). "siRNA knockdown of MRC‐1 or treatment with an anti‐MRC‐1 antibody increased the TNF response to Ply‐expressing S. pneumoniae from DCs and ex vivo alveolar macrophages, as well as in a mouse model of pneumonia." (PMID 35835695, 2022). "Acute pneumonia increased the expression of TNF-α, IFN-γ, IL-6, IL-2 and IL-17 genes, and decreased the expression of Foxp3, IL-10, and TGFβ1 genes in lung tissue homogenate of mice." (PMID 35782123, 2022). "To further evaluate the efficiency of the phages in treating pneumonia, we examined the concentrations of cytokines, including interleukin-1β (IL-1β), IL-6, and tumor necrosis factor alpha (TNF-α), and pathological injuries at 24 and 48 h postinfection." (PMID 36165773, 2022). "Activation of pro-inflammatory (M1) phenotype macrophage is a key parameter of acute pneumonia, which stimulates cytokine storm by releasing proinflammatory factors such as IL-1β, IL-6 and TNF-α." (PMID 36714100, 2022). "In our study, we further extend the function of glutamine in MM by promoting pneumonia, as reflected by enhanced inflammatory responsiveness and an increased secretion of TNF-α." (PMID 36077725, 2022). "For instance, in children with pneumonia, Mycoplasma infection increases the serum concentration of TNFα that is in correlation with the severity of the disease." (PMID 34572059, 2021). "Found in the study, the TNF − α level can predict the occurrence and outcome of pneumonia; therefore, TNF − α plays a key role in the occurrence and development of radiation-induced lung injury." (PMID 35002569, 2021). "When considering intracellular TNF expression after LPS stimulation, alveolar monocytes from pneumonia-related ARDS patients had a significantly lower intracellular TNF expression than non-ARDS patients." (PMID 34944055, 2021). "Recent clinical studies have shown a significant increase in the levels of IL6, TNF, and many other inflammatory factors, especially in patients with severe pneumonia." (PMID 34731090, 2021). "The results showed that 38 compounds in RYNM are involved in the regulation of related target proteins and regulate the IL-17 signalling pathway, TNF signalling pathway, NF-κB signalling pathway and other related pathways to play a role in treating pneumonia." (PMID 33678123, 2021). "In this study, we found that 24 h after the initiation of pneumonia (early stage of infection), PgSup synergistically increased the expression of TNF-α in the lungs of Sp-infected mice." (PMID 34884507, 2021). "Important progress in the understanding of the biological role of the lectin-like domain of TNF comes from in vivo pneumonia and ARDS models evaluating the potential therapeutic potential of the TIP peptide." (PMID 35264975, 2021).
pneumonia (continued). "In patients with severe pneumonia, a very high level of cytokines (IL-6, IL-8, IL-10, and TNF-α) and large subtypes of macrophages have been observed but no activation of NK cells CD8+ T cells is evident." (PMID 34305892, 2021). "Activity of the lectin-like domain of TNF is preserved in complexes between TNF and its soluble TNFRs and can be physiologically relevant in pneumonia." (PMID 35264975, 2021). "Effect of RYNM on serum IL-10, NOS2, COX-1, IL-6, TNF-α and NF-κB levels in pneumonia model rats (mean ± S.D., n = 10)." (PMID 33678123, 2021). "This condition can occur in pneumonia, as such providing a potential explanation for the observed positive effects of TNF in a rat model of severe bacterial pneumonia." (PMID 35264975, 2021). "Influenza virus FM1-infected pneumonia leads to an inflammatory storm, suggesting that many pro-inflammatory cytokines like TNF-α and IL-6 released into blood and lung tissue." (PMID 32625244, 2020). "Proinflammatory cytokines (TNF-α, IL-6 and IL-1β) are considered as major inducers of the inflammatory response and involved in systemic response and local injury during pneumonia." (PMID 33551807, 2020). "Specifically, three targets including IL-1β, IL-6, and TNF-α have been reported to be related to pneumonia, which were further validated in vivo." (PMID 32625244, 2020). "In rodent E. coli pneumonia, E. coli and E. coli-LPS stimulated TNF-a production by alveolar macrophages." (PMID 32685099, 2020). "The incidences of pneumonia were 2.2% and 1.4% using TNF antibodies Infliximab and Etanercept for RA." (PMID 33193322, 2020). "In our study, we found S. aureus infection triggered severe pneumonia, which caused a great rise in pro-inflammatory factors, such as IL-1β, IL-6, TGF-β, MIP-2, MCP-1 and TNF-α in bronchoalveolar lavage fluid." (PMID 33255656, 2020). "In vivo data also indicated that both pN11R and pG31P significantly relieved LPS-induced pneumonia in mice through decreasing the expression of TNF-α, CXCL8, and IL-1β, and inhibiting neutrophil influx into the lung." (PMID 31988368, 2020). "Particularly, since pneumonia and ARDS are associated with a cytokine storm, drugs belonging to therapeutic classes as anti-IL-6, anti-TNF, and JAK inhibitors are currently studied." (PMID 32527304, 2020). "The NIHSS score, white blood cell (WBC) count, rate of pneumonia, and plasma level of IL-6 increased across the tertiles of the GC sensitivity index whereas the TNFα release ex vivo decreased." (PMID 32107751, 2020). "It is noteworthy that TNFα showed a statistically significant increase in the placebo group, but the zinc group had high levels of TNFα at admission with pneumonia that persisted at discharge, comparable to the placebo group in the last measurement." (PMID 31803694, 2019). "The plasma concentrations of 11 inflammatory mediators with pro- and anti-inflammatory activity (IL-1, IL-4, IL-6, IL-8, IL-9, IL-15, eotaxin, bFGF, G-CSF, GM-CSF, and TNF-α) were higher in children with severe CAP than in children with mild pneumonia." (PMID 31183362, 2019). "In a mouse pneumonia model, the host mortality and level of TNF-α in bronchoalveolar lavage fluid were comparable between wild-type and ΔpfbA-infected mice, while deletion of pfbA decreased the bacterial burden in bronchoalveolar lavage fluid." (PMID 31482074, 2019). "Intratracheal inoculation of 1.0 × 108 CFU live S. haemolyticus caused macroscopic and histological confluent pneumonia with significant increase in BAL white cell count, tumor necrosis factor-α (TNF-α), and macrophage inflammatory protein (MIP)-2." (PMID 31636610, 2019). "Cellulitis (n = 25) and pneumonia (n = 24) were the most commonly reported SIs among all patients, with the most cases of cellulitis (n = 22) and pneumonia (n = 17) both reported in the TNF inhibitors cohort." (PMID 31799498, 2019).
pneumonia (continued). "Several studies have associated the excessive production of pro-inflammatory cytokines such as IL-1, IL-6 and TNF-α with the development of M. hyopneumoniae-induced pneumonia." (PMID 31703726, 2019). "In a rat model of pneumonia, IgM-enriched immunoglobulins enhanced the anti-inflammatory response by increasing blood IL-10 levels and reducing TNF-alpha in bronchoalveolar lavage fluid." (PMID 31797105, 2019). "Levels of secreted IL-8 and TNF-α post-infection with S. pneumonia were significantly higher in submerged cultures derived from patients with A-T when compared to that from healthy controls." (PMID 30796268, 2019). "The most common serious infection was pneumonia requiring hospitalization, with a low number of occurrence (one patient in the TNF-alpha group, two in the control group)." (PMID 30658717, 2019). "The data indicated significant differences in the cytokine levels depending on the aetiology of pneumonia: decreased IL-6 for atypical bacteria, increased IL-10 for viral, increased IL-8 for Enterobacter spp., and increased TNF-α for L. pneumophila." (PMID 31183362, 2019). "Relative to other non-macrolide antibiotics, azithromycin reduced levels of IL-6, IL-8, TNF-α and GM-CSF proteins in individuals with pneumonia and rhinovirus infections." (PMID 31306419, 2019). "Increased release of cytokines such as TNF-α together with better survival was observed in mice with pneumonia when iNOS was restored this way." (PMID 30231905, 2018). "Our results showed that serum levels of TNF-α and IFN-γ during infection with MP differed from those observed during infection by other bacterial and viral pathogens causing pneumonia." (PMID 30275916, 2018). "IL-6 is usually highly expressed when cells are stimulated by bacterial LPS, viruses and cytokines such as IL-1, IFN and TNFα, and the concentration of IL-6 and TNFα can reflect the severity of pneumonia." (PMID 28899359, 2017). "A previous study reported that elevated tumor necrosis factor (TNF)-α and interleukin (IL)-6 levels positively correlated with the incidence of pneumonia in healthy elderly individuals." (PMID 28245616, 2017). "The increase of CINC-3 after 20 h of pneumonia and increased levels of TNF-α and IL-6 after 40 h of pneumonia probably reflects the inflammatory reactions during the S. pneumoniae pneumonia." (PMID 27683129, 2016). "In comparison with control mice, animals that received recombinant HMGB1 showed fivefold higher bacilli loads, the double of pneumonia and significant lower expression of IFNγ, TNFα and IL-17, while the expression of IL-10 was significantly higher." (PMID 26201072, 2015). "But a randomized clinical trial of anti-TNF-α treatment for severe asthmatics was terminated early because of serious drug side effects, such as pneumonia and malignancy." (PMID 25658739, 2015). "The related research by Janek Henes's indicates that NF-κB activation accelerates the increase of alveolar-capillary permeability during TNF-α-induced pneumonia in VASP knockout mice." (PMID 25051011, 2014). "IL-6, MCP-1 and TNFα levels were all significantly decreased 24 hours after pneumonia in aged septic Mttp-IKO mice." (PMID 25010671, 2014). "In mechanically ventilated patients, Montón and colleagues found that serum TNF-α level was significantly higher in patients with pneumonia compared with controls." (PMID 23577187, 2013). "Thus, TNF-α −238A/G polymorphism may play a possible role in the pneumonia-related mortality." (PMID 23577187, 2013). "The levels of several pro- and anti-inflammatory cytokines (including IL-1β, IL-6, IL-10, IL-13, G-CSF and TNFα) were examined in BAL fluid 24 hours after the onset of pneumonia in both genotypes." (PMID 23145105, 2012). "We previously showed that Pigeon04 highly induced the expressions of pro-inflammatory cytokines such as IL6 and TNFα in the lungs of the infected mice, resulting in severe pneumonia." (PMID 21826229, 2011).
pneumonia (continued). "The highest values for TNF-α and CRP levels were observed in patients with pneumonia caused by Streptococcus pneumoniae and Legionella pneumophila." (PMID 16899118, 2006). "In HAP patients with subsequent septic shock, IL-1β, IL-6, IL-8 and IL-10 were superior predictive markers than TNF-α, E-selectin and conventional laboratory values and scores at the time of pneumonia diagnosis." (PMID 16280065, 2005). "At the 'diagnosis of pneumonia', TNF-α, IL-1β, IL-6, IL-8, IL-10 and E-selectin were significantly increased in those patients who had subsequent septic shock, compared to patients with pneumonia without subsequent septic shock." (PMID 16280065, 2005). "• At the time of HAP diagnosis, TNF-α, IL-1β, IL-6, IL-8, IL-10 and E-selectin were significantly increased in pneumonia patients with subsequent septic shock compared to patients without subsequent septic shock." (PMID 16280065, 2005). "In our opinion, this is the first study to identify SNPs in antioxidant (SOD1, CAT, GPX1, NOS, HMOX1, and NQO1) and immunological (IL-1α, IL1B, IL6, TNF-α, IL10, LFA-1, CR2, IL17, IL13, DEFB123, SCART1, and ICAM1) genes as potential suspects for pneumonia resistance/susceptibility in Barki ewes." (PMID 40221769, 2025). "With advances in nanotechnology, Noh and colleagues developed cellular nanodiscs derived from P. aeruginosa OMVs, which enhanced both cellular and humoral immune responses, protecting against pneumonia by reducing the lung bacterial loads and pro-inflammatory cytokines (IL-12, IL-17A and TNF-α)." (PMID 40076637, 2025). "In addition, Machado showed that green propolis reduced the levels of IL-6 and TNF-α in pneumonia induced by LPS." (PMID 40430449, 2025). "In our study, TNF-α levels were significantly higher in patients with pneumonia, particularly in those with ARDS, compared to healthy controls, demonstrating 93.3% sensitivity and 86.7% specificity at a threshold of>442 pg/ml for predicting ARDS in children with community-acquired pneumonia." (PMID 41382116, 2025). "Consequently, the TNF/NF‐κB/MAPKs signaling pathway was selected to investigate the potential mechanisms by which ganodermanontriol treats pneumonia." (PMID 40144560, 2025). "Both pneumonia and GI sepsis trigger a robust systemic inflammatory response characterized by the release of pro-inflammatory cytokines such as interleukin-6 (IL-6) and tumor necrosis factor-alpha (TNF-α)." (PMID 39258039, 2024). "There were a total of ten pneumonia-related pathways, which were TNF signaling, MAPK signaling pathway, chemokine signaling, NF-κB signaling, mTOR signaling, VEGF signaling, autophagy-animal, Toll-like receptor signaling, FoxO signaling, and NOD-like receptor signaling." (PMID 38671867, 2024). "TNFα recruits neutrophils, reducing the incidence of bacteraemia in a mouse pneumonia model." (PMID 36897919, 2023). "Bacteremic patients have higher levels of TNF circulating in the serum compared to pneumonia alone." (PMID 36870980, 2023). "Moreover, IgM-enriched immunoglobulins were shown to enhance the anti-inflammatory response by increasing IL-10 levels and reducing the TNF-alpha in the bronchoalveolar lavage fluid of pneumonia models." (PMID 37959352, 2023). "In the absence of TNF, opportunistic bacterial pathogens such as Legionella pneumophila, which causes the severe pneumonia Legionnaires’ disease, readily invade and replicate inside innate immune cells known as macrophages." (PMID 37279255, 2023). "Interestingly, high levels of NO, IL-6 and TNF-α expression in a mouse model of pneumonia were effectively lowered after treatment with polyphenol-rich extract from M. officinalis bark, which also provided long-term protection against reinfection." (PMID 36278162, 2022). "HUC-MSC treatment reduced IL-1β and TNF-α levels in acute pneumonia mice." (PMID 36260750, 2022).